RFPL3 (ret finger protein like 3)
Diseases named in the same sentence as RFPL3 in open-access papers (continued):
Sharing a sentence is not in itself a finding about the gene and the disease.
breast carcinoma (1 paper, 2022). "Collectively, our study findings indicated that CBP coordination with RFPL-3 promotes ASC-induced breast cancer cell proliferation by anchoring to the hTERT promoter and upregulating telomerase activity, which is activated by the MAPK/ERK pathway." (PMID 35711680, 2022). "The inhibition of CBP and RFPL-3 suppressed the proliferation of breast cancer cells cocultured with ASCs following decreases in hTERT transcriptional activity in vitro and in vivo." (PMID 35711680, 2022). "The inhibition of CBP and RFPL-3 abrogated the activation of hTERT transcription and the promotion of proliferation in breast cancer cells with cocultured ASCs in vitro and in vivo." (PMID 35711680, 2022). "Taken together, our findings clearly demonstrate that the depletion of CBP and RFPL-3 inhibits ASC-induced proliferation of breast cancer cells through the suppression of hTERT." (PMID 35711680, 2022). "In summary, our findings have shown that CBP coordinates with RFPL-3 to promote ASC-induced breast cancer cell proliferation by anchoring to the hTERT promoter and upregulating telomerase activity, which is activated by the MAPK/ERK signaling pathway." (PMID 35711680, 2022). "Given this background, we explored whether CBP and RFPL-3 could coregulate hTERT transcription in the ASC-stimulated breast cancer cell proliferation." (PMID 35711680, 2022). "Accordingly, to detect the proteins on the hTERT promoter in breast cancer cells, we performed a ChIP assay and found that the RFPL-3 proteins bound to the hTERT promoter region in breast cancer cells, especially MDA-MB-231 cells, were higher than that in normal breast cells." (PMID 35711680, 2022). "In line with our hypothesis, the results showed that overexpressed CBP did indeed regulate the ASC-stimulated breast cancer cell proliferation by activating the binding of RFPL-3 to the hTERT promoter region and enhancing telomerase activity." (PMID 35711680, 2022). "However, the precise mechanisms of the CBP regulation of RFPL3-mediated hTERT activity and proliferation of breast cancer cells remain unknown, especially regarding the action of ASCs." (PMID 35711680, 2022).
tumor (4 papers, 2014 to 2022). "Inhibition of RFPL3 by siRNA or shRNA also significantly inhibited tumor cell growth in vitro and in a xenograft mouse model in vivo." (PMID 25481043, 2014). "Moreover, combining with our previous study, the accumulation of RFPL3 in the nucleus will lead to the upregulation of hTERT transcription and the further aggravation of the malignant degree of the tumor." (PMID 33082305, 2020). "Chromatin immunoprecipitation confirmed RFPL3 as a tumor-specific hTERT promoter binding protein." (PMID 25481043, 2014). "It is obvious that RFPL3, CBP and hTERT proteins were upregulated in tumor tissues from most cases compared with the normal adjacent lung tissues." (PMID 26318425, 2015).
cancer (2 papers, 2014 to 2015). A tumor composed of atypical neoplastic, often pleomorphic cells that invade other tissues. "However, the molecular expression and function of RFPL protein family, including RFPL3, in cancers are still unclear." (PMID 26318425, 2015). "However, the molecular expression and the function of other RFPL proteins family members including RFPL3 in cancers are still unclear." (PMID 25481043, 2014). "However, the upregulation of RFPL3 protein also can not completely account for the cancer-specific overexpression of hTERT in NSCLC." (PMID 25481043, 2014).